DUSP3 (dual specificity phosphatase 3)
Description:
Shows activity both for tyrosine-protein phosphate and serine-protein phosphate, but displays a strong preference toward phosphotyrosines. Specifically dephosphorylates and inactivates ERK1 and ERK2.
Synonyms: VHR
Tractability: Small molecule: a structure with a bound ligand is known; a high-quality ligand is known; it belongs to a druggable protein family. PROTAC: ubiquitination databases record sites on it; its protein half-life has been measured; a small molecule that binds it is known.
Target class: Phosphatase; Serine/threonine/tyrosine protein phosphatase; Enzyme; Protein Phosphatase
Chemical probes: ML113
Gene: Protein-coding gene on chromosome 17 (43,766,121 to 43,779,000, reverse strand). Ensembl gene ENSG00000108861.
Subcellular location: Nucleus; Cytoplasm, cytoskeleton, flagellum axoneme
Subcellular location (Human Protein Atlas): Nucleoplasm; Cytosol
Pathways (Reactome):
Signal Transduction: ERKs are inactivated
Gene Ontology:
Molecular function: cytoskeletal protein binding; MAP kinase phosphatase activity; phosphatase activity; protein binding; protein kinase binding; protein serine/threonine phosphatase activity; protein tyrosine kinase binding; protein tyrosine phosphatase activity; protein tyrosine/serine/threonine phosphatase activity; receptor tyrosine kinase binding; receptor signaling protein tyrosine kinase inhibitor activity
Biological process: cellular response to epidermal growth factor stimulus; dephosphorylation; negative regulation of cell migration; negative regulation of chemotaxis; negative regulation of ERK1 and ERK2 cascade; negative regulation of JNK cascade; negative regulation of MAPK cascade; negative regulation of T cell activation; negative regulation of T cell receptor signaling pathway; peptidyl-tyrosine dephosphorylation; positive regulation of focal adhesion disassembly; positive regulation of mitotic cell cycle; regulation of focal adhesion assembly; negative regulation of epidermal growth factor receptor signaling pathway; negative regulation of signal transduction
Cellular component: cytosol; immunological synapse; nucleoplasm; nucleus; cytoplasm
Genetic constraint (gnomAD): Loss-of-function variants: 7 observed, 12.39 expected, observed/expected ratio (o/e) 0.57, 90% interval 0.32 to 1.06. The upper end of that interval is the gene's LOEUF score, 1.06, which puts it in group 4 of 6, group 1 being the genes least tolerant of losing a copy. Missense variants: 209 observed, 239.93 expected, observed/expected ratio (o/e) 0.87, 90% interval 0.78 to 0.98. Synonymous variants: 86 observed, 94.83 expected, observed/expected ratio (o/e) 0.91, 90% interval 0.76 to 1.09.
Homologues: Orthologues: chimpanzee DUSP3 (100% identical), dog DUSP3 (98% identical), pig DUSP3 (96% identical). Paralogues in human: DUSP13A (41% identical), DUSP13B (41% identical), DUSP29 (41% identical), DUSP26 (39% identical), STYXL2 (35% identical), DUSP2 (32% identical), SSH3 (32% identical), DUSP1 (31% identical), DUSP4 (31% identical), DUSP7 (30% identical), DUSP10 (30% identical), DUSP9 (30% identical), and 19 more.
Diseases named in the same sentence as DUSP3 in open-access papers:
DUSP3 is named in the same sentence as 61 diseases in open-access papers, as found by Europe PMC text mining. Sharing a sentence is not in itself a finding about the gene and the disease. The quoted sentences say what the papers report.
tuberculosis (7 papers, 2019 to 2025). A chronic, recurrent infection caused by the bacterium Mycobacterium tuberculosis. "Here, a three-gene set (GBP5, DUSP3, and KLF2) in the host whole blood that is robustly diagnostic for active tuberculosis was studied using multiple independent cohorts comprised of children and adults." (PMID 36010011, 2022). "Second, DUSP3 mRNA was identified as part of a transcriptional signature for the diagnosis of tuberculosis from human peripheral blood in two independent studies." (PMID 31159473, 2019). "Remarkably, DUSP3 belonged to a set of three genes (with GBP5 and KLF2) that were diagnostic for active tuberculosis in eight independent datasets from ten countries." (PMID 31159473, 2019). "This diagnostic correlation of DUSP3 expression in peripheral blood cells with active tuberculosis has not been linked to a function of this phosphatase in the host yet." (PMID 31159473, 2019). "Expression of the 3-gene signature, [guanylate-binding protein (GBP5), dual specificity phosphatase 3 (DUSP3) and Krupple-like factor 2 (KLF2)] was quantified and a tuberculosis (TB) score was calculated using (GBP5+DUSP3)/2-KLF2." (PMID 41430759, 2025). "A novel 3-gene host transcriptional signature (GBP5, DUSP3 and KLF2) has been validated for tuberculosis (TB) treatment monitoring using laboratory-based RNA sequencing platforms." (PMID 34193258, 2021).
breast carcinoma (5 papers, 2017 to 2023). "However, DUSP3 is also downregulated in other cancers such as breast cancer and non-small cell lung carcinoma (NSCLC), indicating contradictory and complex roles of DUSP3 in cancer development." (PMID 29020102, 2017). "Repression of DUSP3 expression increased the phospho-ERK1/2 levels in HeLa cells, non–small cell lung cancer cells(H1792 and H460) and breast cancer cells(MCF-7 and SKBR3)." (PMID 30048472, 2018).
melanoma (5 papers, 2017 to 2024). A malignant, usually aggressive tumor composed of atypical, neoplastic melanocytes. "Interestingly, DUSP1, -8 and -9 appear to be downregulated and DUSP3 is upregulated in LNM WM165-1 compared to primary melanoma and other LNM derived cells." (PMID 35999349, 2022). "To verify whether the marked increase of LLC growth in DUSP3-/- mice was tumour model-dependent, we challenged DUSP3+/+ and DUSP3-/- with two additional metastatic cells such as melanoma B16-F10-luciferase (B16) cells and E0771 cells." (PMID 29020102, 2017). "Similarly, the up-regulated genes in the ABCB5 CTC fractions were involved in metastasis (CALU, CYB5R1, DUSP3, CREG1, ENDOD1), tumour growth, and/or melanoma biology (H1F0, SCNA, WIPI1, TXN2)." (PMID 30769764, 2019).
non-small cell lung carcinoma (5 papers, 2014 to 2022). A group of at least three distinct histological types of lung cancer, including non-small cell squamous cell carcinoma, adenocarcinoma, and large cell carcinoma. "DUSP3 downregulation occurs in human non-small cell lung cancer patients; consistently, DUSP3 deficiency results in enhanced cancer cell migration." (PMID 31151270, 2019). "A previous study has also reported that DUSP3 has a minimal effect on MAPK phosphorylation but rather target directly EGFR in non-small cell lung cancer cell line." (PMID 24886454, 2014). "Previously we showed that DUSP3 expression was decreased in non-small cell lung cancer tissues." (PMID 35705979, 2022).
lung carcinoma (4 papers, 2014 to 2025). "Animal and clinical data were analyzed for the association between DUSP3 deficiency and lung cancer progression." (PMID 35705979, 2022). "Overexpression of KDM2A in lung cancer was associated with poor prognosis and is believed to promote lung tumorigenesis by repressing DUSP3 (dual-specificity phosphatase 3) and activating ERK1/2." (PMID 25029110, 2014). "Our data implicated the loss of DUSP3 expression in lung cancer may participate in the tumorigenic process." (PMID 35705979, 2022). "Parallelly, we demonstrated that the inhibition of DUSP3 is crucial for TC2N to exert its role in promoting the stemness of lung cancer cells by either overexpressing DUSP3 alone in original cells or interfering with DUSP3 expression in TC2N-silenced cells." (PMID 39849581, 2025). "Regarding the mechanism of the tumor-promoting role of TC2N in lung cancer, we showed that the interaction between DUSP3 and TC2N blocked DUSP3’s interaction with its substrates and inhibited its enzymatic activity." (PMID 39849581, 2025). "Co-IP assays using DUSP3 antibody in stable lung cancer cell lines showed that TC2N overexpression reduced the interaction between endogenous DUSP3 and its substrates." (PMID 39849581, 2025). "In prostate cancer and cervix cancer, DUSP3 serves as tumor-promoting phosphatase, oppositely, its execute a tumor suppressor function in breast and lung cancer." (PMID 39849581, 2025). "In lung cancer, the dual-specificity protein phosphatase 3 (DUSP3) expression is suppressed by KDM2A-dependent H3K36 demethylation at its promoter, which raises ERK1/2 and JNK1/2 functions." (PMID 37218871, 2023). "We hypothesized that TC2N may enhance the phosphorylation of these proteins by blocking DUSP3 in lung cancer cells." (PMID 39849581, 2025). "Decreasing DUSP3 expression is observed in several type of cancers, including lung cancer." (PMID 35705979, 2022). "Analysis of two independent large sample lung cancer GEO datasets (GSE11969 and GSE68465) showed that DUSP3 expression was lower in well-differentiated tumors compared to poorly-differentiated tumors." (PMID 39849581, 2025). "Dual specificity phosphatase 3 (DUSP3), a suppressor of multiple protein tyrosine (Tyr) kinases, is decreased in lung cancer tissues." (PMID 35705979, 2022). "DUSP3 also dephosphorylates epidermal growth factor receptor (EGFR), suppresses tumor formation by lung cancer cells, and its expression levels are decreased in lung cancer tissues." (PMID 35705979, 2022). "Despite the multiple effects of DUSP3 seemed to support a tumor-suppressive role, we did not observe lung cancer (or other tumors) formation in DUSP3−/− mice during the life span examined (up to 18 months)." (PMID 35705979, 2022).
acute myocardial infarction (3 papers, 2024 to 2025). Necrosis of the myocardium, as a result of interruption of the blood supply to the area. "For instance, DUSP3 loss‐of‐function relieves acute myocardial infarction damage through suppressing inflammation and apoptosis." (PMID 38629726, 2024). "Recent findings have determined the presence of DUSP3 in the progression of Acute Myocardial Infarction (AMI) and it has been shown that DUSP3 knockdown alleviates oxidative stress, inflammation, and apoptosis." (PMID 40591616, 2025). "Dual specificity phosphatase 3 (DUSP3) regulates MAP kinases, is required to maintain epithelial tight junctions, decreases myocardial infarction induced apoptosis and inflammation, and modulates thrombosis, hemostasis and angiogenesis." (PMID 41353157, 2025).
carcinoma of the cervix (3 papers, 2011 to 2014). "Dusp3 also regulates cell death and cell proliferation, exhibiting anti-apoptotic ability in prostate cancer cells and promoting cell cycle progression in carcinoma of the cervix." (PMID 24901344, 2014). "Upregulated expression and nuclear localization of DUSP3 promotes the pathogenesis of cervix carcinoma." (PMID 22140479, 2011). "Indeed, we reported that DUSP3 is highly expressed in cervical carcinomas and in several cervix cancer cell lines." (PMID 24886454, 2014).
endotoxemia (3 papers, 2018 to 2024). "In the research on sepsis, it was found that DUSP3 deficiency protects mice from endotoxemia and multimicrobially induced septic shock." (PMID 38629726, 2024). "As reported, DUSP3 deficiency protects mice from endotoxemia and multimicrobially induced septic shock." (PMID 38629726, 2024). "For example, dual-specificity phosphatase 3 (DUSP3) is linked to estrogen-mediated modulation of the macrophage response, thereby protecting female rats from endotoxemia-induced and polymicrobial-induced septic shock." (PMID 36985319, 2023).
glioma (3 papers, 2022 to 2023). A benign or malignant brain and spinal cord tumor that arises from glial cells (astrocytes, oligodendrocytes, ependymal cells). "MicroRNA miR-1246 released from exosomes in gliomas upregulates the DUSP3/ERK pathway, leading to activation of the immunosuppressive function of M-MDSCs." (PMID 38275375, 2023). "Although high expression of exosomal miR-1246 is known to correlate with pathological tumor grade and inversely with prognosis in various cancers, the precise role of this microRNA and DUSP3 signaling in glioma biology needs further investigation." (PMID 38275375, 2023). "miR-1246 in glioma-derived exosomes was demonstrated to mediate MDSC differentiation and activation in a dual-specificity phosphatase 3 (DUSP3)/extracellular signal‐regulated kinase (ERK)-dependent mechanism." (PMID 35634311, 2022).
Sepsis (3 papers, 2014 to 2024). Sepsis is defined as life-threatening organ dysfunction caused by a dysregulated host response to infection. "Dehydroandrographolide exerts an alleviating effect on sepsis‐associated acute kidney injury, likely resulting from the promotion of M2 macrophage polarization by downregulating DUSP3." (PMID 38629726, 2024). "Particularly, DUSP3 expression was conspicuously upregulated in the renal tissues of mice in the sepsis group, and Deh addition downregulated DUSP3 expression." (PMID 38629726, 2024). "The in vivo results suggested that Deh improved the renal function, ameliorated pathological injury, induced the polarization of M1 macrophages to M2, suppressed inflammation and apoptosis, and downregulated DUSP3 expression in sepsis‐induced mice." (PMID 38629726, 2024). "Above results together suggested that Deh could protect against sepsis‐associated AKI in vitro and in vivo by facilitating M2 macrophage polarization by downregulating DUSP3." (PMID 38629726, 2024). "f) Nees, could protect against sepsis‐associated AKI in vitro and in vivo by facilitating M2 macrophage polarization by downregulating DUSP3." (PMID 38629726, 2024). "AlthoughSTK4 (serine/threonine kinase 4) and DUSP3 (dual specificityphosphatase 3) were only target genes of miR-193b*, these two genes werealso selected because the level of miR-193b* had the highest predictivevalue of sepsis mortality." (PMID 24303815, 2014).
hepatocellular carcinoma (2 papers, 2021 to 2022). A malignant tumor that arises from hepatocytes. "This was consistent with a recent report that DUSP3−/− mice did not develop hepatocellular carcinoma unless combined with the treatment of high-fat diet or a liver carcinogen diethyl nitrosamine (DEN)." (PMID 35705979, 2022).
Lewis Lung carcinoma (2 papers, 2017 to 2021). "In this study, using a Lewis Lung carcinoma (LLC)-experimental metastasis model and DUSP3-deficient mice, we reported that the phosphatase DUSP3 is a key player in metastatic growth, modulating the recruitment of macrophages towards LLC-bearing lungs." (PMID 29020102, 2017). "Using a Lewis Lung carcinoma (LLC) experimental metastasis model, we observed that DUSP3-/- mice developed larger lung metastases than littermate controls." (PMID 29020102, 2017).
lung adenocarcinoma (2 papers, 2022 to 2025). A carcinoma that arises from the lung and is characterized by the presence of malignant glandular epithelial cells. "DUSP3 deficiency was associated with worse outcomes of lung adenocarcinoma in experimental animals and in patients." (PMID 35705979, 2022). "Because of the frequent loss of TJ in transformation of epithelial tissues, we interbred DUSP3-knockout mice with EGFR-Del transgenic (Tg) mice and examined the effect of DUSP3 deficiency in lung adenocarcinoma (LAC) progression." (PMID 35705979, 2022).
Obesity (2 papers, 2021 to 2022). Accumulation of substantial excess body fat. "In this study, using DUSP3-full body knockout mice, we uncovered a critical role of DUSP3 in the development of obesity, NAFLD and associated disorders, and in insulin resistance." (PMID 33712680, 2021). "In conclusion, our results support a new role for DUSP3 in obesity, insulin resistance, NAFLD and liver damage." (PMID 33712680, 2021). "A prominent phenotype of DUSP3-KO mice was the development of late-onset obesity and insulin resistance under regular chow diet (CD), a phenotype exacerbated under HFD." (PMID 33712680, 2021). "In summary, although we clearly need to further investigate the possibility that other signaling defects may also contribute to the obese phenotype of the DUSP3-KO animals, the data presented indicate a prominent role for defective IR signaling in the development of obesity and NAFLD in these mice." (PMID 33712680, 2021). "For example, DUSP3 deletion contributes to higher ERK and p38 phosphorylation, thereby promoting obesity and NASH in HFD-fed mice." (PMID 36209205, 2022). "Unlike many other animal models available, development of obesity is not accompanied by hyperphagia in DUSP3-KO mice." (PMID 33712680, 2021).
staphylococcus aureus infection (2 papers, 2014 to 2022). An infectious process in which the bacteria Staphylococcus aureus is present. "DUSP3 plays a role in Staphylococcus aureus infection, DUSP3, a positive regulator of innate immune response, is the main protein tyrosine phosphatase in macrophages mediating cellular processes (including immune responses)." (PMID 35045818, 2022).
abdominal aortic aneurysm (1 paper, 2025). Enlargement and ballooning of the vessel that supplies arterial blood to the abdomen, pelvis and legs. "The present studies have implicated the phosphoprotein phosphatase DUSP3 as a critical determinant of abdominal aortic aneurysm formation." (PMID 40100302, 2025). "Administration of the DUSP3 inhibitor completely blocked the development of abdominal aortic aneurysms in d-alanine–fed DAAO-TGTie2 mice." (PMID 40100302, 2025).
autoimmune disease (1 paper, 2026). A disorder resulting from loss of function or tissue destruction of an organ or multiple organs, arising from humoral or cellular immune responses of the individual to their own tissue constituents. "Downregulation of DUSP1, DUSP3, DUSP11, and DUSP22, as well as upregulation of DUSP4, DUSP6, and DUSP23 are involved in human autoimmune diseases." (PMID 42087139, 2026).
cardiomyopathy (1 paper, 2025). A disease of the heart muscle or myocardium proper. "Additionally, a disease–gene association circos plot generated using RAW Graphs 2.0 showed tight linkage of hub DEGs such as DAPK2, DUSP3, IL6R, and UGP2 to cardiovascular comorbidities, including heart failure, diabetic retinopathy, cardiomyopathy, and pulmonary hypertension." (PMID 41262879, 2025).
colon cancer (1 paper, 2017). "DUSP3 (DUal Specificity protein Phosphatase 3) was the other influencer protein that we found in all five databases for colon cancer." (PMID 28603644, 2017).
dementia (1 paper, 2015). Loss of intellectual abilities interfering with an individual's social and occupational functions. "The expression of enzymes that are involved in cell metabolism, such as DUSP3 and PDHE1-B, changed in a dementia mouse model and after Aβ1–42 treatment in vitro, respectively." (PMID 25978363, 2015).
gram-negative bacterial infections (1 paper, 2014). Infections caused by bacteria that show up as pink (negative) when treated by the gram-staining method. "Finally, Dusp3 homozygous mutant mice exhibited susceptibility to Gram negative bacterial infection in screening results from the Knockout Mouse Consortium program." (PMID 24901344, 2014).
Hepatic steatosis (1 paper, 2022). Steatosis is a term used to denote lipid accumulation within hepatocytes. "According to our current findings, previous studies, and the characteristic of DUSPs family, we demonstrated that the dephosphorylating capacity of DUSPs family members (DUSP22, DUSP3, DUSP9, DUSP12, DUSP14, DUSP26, etc) might be indispensable for its protective role against hepatic steatosis." (PMID 36209205, 2022).
Hypertension (1 paper, 2025). The presence of chronic increased pressure in the systemic arterial system. "The DUSP3 inhibitor also markedly attenuated the hypertension caused by d-alanine feeding in DAAO-TGTie2 mice; there was still a small but statistically significant increase in blood pressure in the DUSP3-treated d-alanine–fed DAAO-TGTie2 mice compared with the negative controls." (PMID 40100302, 2025).